BRCA2 (BRCA2 DNA repair associated)
Diseases named in the same sentence as BRCA2 in open-access papers (continued):
Sharing a sentence is not in itself a finding about the gene and the disease.
breast cancer (continued). "Although the pancreatic cancer pathway appears not to be associated with breast cancer, some reports have determined that mutations in the BRCA2 gene have been implicated in pancreatic cancer susceptibility through studies conducted on high-risk breast and ovarian cancer families." (PMID 25961039, 2015). "However, the contribution of the BRCA1 or BRCA2 mutation in breast cancer incidence has not yet been investigated in Argentina." (PMID 25624909, 2015). "Among these, approximately 10% of breast cancer patients have a family history of breast cancer (referred as familial breast cancer), but only 10–15% of familial breast cancer is owing to germline mutations in one of the two high penetrance breast cancer susceptibility genes—BRCA1 and BRCA2." (PMID 25945795, 2015). "However, the expression of canine BRCA2 in mammary tumors is unclear." (PMID 26202431, 2015). "In addition to the main effects, interaction between HMMR and AURKA, and between HMMR and TUBG1 could influence breast cancer risk in BRCA1 and BRCA2 mutation carriers." (PMID 25830658, 2015). "Therefore, we performed an updated meta-analysis to aim to come up with the highest level of evidence for the associations between three SNPs in TOX3 gene and breast cancer risk among diverse ancestry populations and distinct tumor subtypes stratified by estrogen receptor (ER) or BRCA1/BRCA2." (PMID 26239137, 2015). "However, in canine mammary tumors, little is known about BRCA2 expression." (PMID 26202431, 2015). "The biological background of BRCA1/2 and different pathological aspects of BRCA1-associated tumours support the hypothesis that patients carrying a BRCA1 and/or BRCA2 mutation might have a worse breast cancer prognosis compared to non-carriers." (PMID 25816289, 2015). "However, it has been reported that FA gene mutations, other than in BRCA2, are unlikely to be a frequent cause of highly penetrant breast cancer predisposition." (PMID 25093046, 2014). "Moreover, our results show that, to a large extent, the differences in breast cancer associations of known breast cancer susceptibility loci between BRCA1 and BRCA2 carriers and the general population are due to differences in the prevalence of tumor subtypes in BRCA1 and BRCA2 carriers." (PMID 25919761, 2014). "In this report, we investigated genome-wide RNA profiles of tumors from familial breast cancer cases where no BRCA1 or BRCA2 mutations could be identified by traditional genetic analysis for germline mutations." (PMID 24479546, 2014). "Given their important role in breast cancer predisposition, it is timely that genetic testing include the evaluation of mutations in these additional 23 genes, and not only mutations in BRCA1 and BRCA2, which represents the current testing protocol in cancer genetic clinics." (PMID 24667084, 2014). "In contrast, in the majority (90%) of sporadic breast cancers, BRCA2 is not mutated." (PMID 24289229, 2013). "Previously reported BRCA2-modifying alleles for breast cancer, including those in FGFR2, TOX3, MAP3K1, LSP1, 2q35, SLC4A7, 5p12, 1p11.2, ZNF365, and 19p13.1 (ER-negative only), are also associated with breast cancer risk in the general population and/or BRCA1 mutation carriers." (PMID 23544012, 2013).
breast cancer (continued). "However, in high-risk families, these breast cancer risk factors may be secondary to mutations in the breast cancer associated (BRCA) genes, i.e. BRCA1 and BRCA2." (PMID 23922822, 2013). "Apart from KL and PARP4, the 13q linkage peak also includes known candidate genes for inflammation, e.g., arachidonate 5-lipoxygenase-activating protein (ALOX5AP), and cancer, e.g., breast cancer 2 early onset (BRCA2), all of which may be involved in the aging process." (PMID 24036517, 2013). "However, the phenotype of BRCA2 mutation-related breast cancer is still difficult to distinguish from non-BRCA mutation-related breast cancers." (PMID 23409121, 2013). "To seek additional breast cancer risk modifying loci for BRCA2 mutation carriers, we conducted an extended replication of the GWAS discovery results in a larger set of BRCA2 mutation carriers in CIMBA, which represents the largest, international collection of BRCA2 mutation carriers." (PMID 23544012, 2013). "The aim of the current study was to analyze whether female index individuals of breast cancer families who had tested negative for germline mutations in BRCA1/BRCA2 as part of genetic counseling services should be offered mutation testing for PALB2 c.1592delT." (PMID 23941127, 2013). "One SNP, rs9348512 at 6p24 not known to be associated with breast cancer, had a combined P-value of association of 3.9×10−8 amongst all BRCA2 samples, with strong evidence of replication in the set of BRCA2 samples that were not used in the discovery stage (P = 5.2×10−5)." (PMID 23544012, 2013). "Using a custom genotyping platform with 211,155 genetic variants known as single nucleotide polymorphisms (SNPs), we genotyped 3,881 women who had breast cancer and 4,330 women without breast cancer, which represents the largest possible, international collection of BRCA2 mutation carriers." (PMID 23544012, 2013). "There are over 10 genes causing hereditary forms of breast cancer (BC), however only BRCA1- and BRCA2-related disease has been studied with sufficient level of comprehension." (PMID 23548133, 2013). "Somatic PIK3CA mutation is present in familial male breast cancer but absent in BRCA2 carriers." (PMID 23971979, 2013). "Potentially, the signatures could also be used as a tool for preselecting patients for mutation screening, as a significant proportion of BRCA1 and BRCA2 germline mutation carriers do not have a family history of breast cancers." (PMID 23704984, 2013). "In BRCA2 mutation carriers, evidence for a breast cancer association with genetic variants in PTHLH has been restricted previously to ER-negative tumors; however, the novel susceptibility variant we reported here was associated with risk of ER+ and ER- breast cancer." (PMID 23544012, 2013). "Thus, as the incidence of PIK3CA mutations in tumours from in BRCA2 carriers is likely to be negligible, these patients are unlikely to derive benefits from the PIK3CA inhibitors that are now entering clinical trials for female breast cancer." (PMID 23971979, 2013). "However, clearly deleterious mutations in the canine BRCA2 sequence have not been identified in mammary tumors due to the lack of appropriate methods to detect such mutations." (PMID 22471976, 2012). "In contrast to Hollestelle and colleagues, who found increased frequency of the KRAS variant among cases from BRCA1 positive families, we did not observe an association between the KRAS variant and either cases from BRCA1, BRCA2 or non-BRCA breast cancer families." (PMID 22436609, 2012). "In addition, we evaluated whether rs2180341 modifies breast cancer risk in 3,361 BRCA1 and 2,020 BRCA2 carriers from 11 centers in the Consortium of Investigators of Modifiers of BRCA1/2 (CIMBA)." (PMID 22768030, 2012).
breast cancer (continued). "In the present study, we investigated the germline CNV profiles of 68 unrelated familial and early-onset breast cancer patients who were negative for BRCA1/BRCA2 mutations, with the aim of detecting new genes contributing to breast and/or ovarian cancer predisposition." (PMID 22314128, 2012). "However, clearly deleterious BRCA2 mutations have not been identified in any canine mammary tumors, as appropriate methods to detect mutations or a consensus BRCA2 sequence have not been reported." (PMID 22471976, 2012). "While the risk for second primaries has been studied in BRCA1 or BRCA2 mutation carriers, preliminary data indicate that the risk of contralateral breast cancer is not significantly elevated in patients with familial breast cancer, who tested negative for BRCA1/2 mutations." (PMID 23216834, 2012). "Since we were unable to detect any of our novel fusions in our screening of additional BRCA1-mutated, BRCA2-mutated or BRCA1/2-unrelated breast cancers, they may represent non-recurrent passenger mutations." (PMID 22032724, 2011). "The CHEK2-Breast Cancer Consortium reported a frequency of 5.1% for the CHEK2*1100delC variant in familial breast cancer cases who tested negative for BRCA1 and BRCA2 (Breast cancer 2, early onset) mutations, as opposed to 1.1% of carriers in the control population." (PMID 21569354, 2011). "We aimed to assess whether CHEK2 was subject to DAE in lymphoblastoid cell lines (LCLs) from high-risk breast cancer patients for whom no mutation in BRCA1 or BRCA2 had been identified." (PMID 21569354, 2011). "For subgroups defined by mutation status of the index case, the non-breast cancers SIR for relatives of the index cases who carried BRCA1 mutations was marginally elevated while the SIR for relatives of the index cases who carried BRCA2 mutations was not elevated." (PMID 20877337, 2010). "It is of interest, however, that when utilizing an agnostic approach in BRCA2 mutation carriers in this study, the major determinants of risk variation in mutation carriers are those that also modify risk in subsets of sporadic, BRCA1/2 wild type, breast cancer." (PMID 21060860, 2010). "To identify predictors of pathogenic mutation status in familial breast cancer patients, we explored the use of gene expression arrays to assess the effect of two DNA–damaging agents (irradiation and mitomycin C) on cellular response in relation to BRCA1 and BRCA2 mutation status." (PMID 20174566, 2010). "In a subgroup analysis of the National Surgical Adjuvant Breast and Bowel Project (NSABP-P1) trial, Tamoxifen was found to reduce the incidence of breast cancer in healthy BRCA2 mutation carriers but not in BRCA1 carriers when started at the age 35 years or older." (PMID 20961453, 2010). "However, to prove the possibility of genetic susceptibility in relation to any survival difference across type of breast cancer molecular genetic studies such as BRCA1 and BRCA2 in association with survival, although the results are inconsistent, are still required." (PMID 19190627, 2009).
breast cancer (continued). "Evaluation of the overall survival curves using the Kaplan-Meier method indicated that patients carrying BRCA2 mutations presented a lower breast cancer-specific survival in comparison with those resulted negative for BRCA2 mutations, within the first two years from diagnosis." (PMID 19232099, 2009). "By careful selection of family members to be typed, i.e. early breast cancer cases distantly related to the proband and old healthy individuals nearby, segregation analysis will be a powerful tool to assess the clinical significance of unclassified variants in BRCA1 and BRCA2." (PMID 19563646, 2009). "However a retrospective study demonstrated a 50% reduction in risk of contralateral breast cancer for both BRCA1 (odds ratio = 0.50: 95% CI, 0.30–0.85) and BRCA2 (odds ratio = 0.42: 95% CI, 0.17–1.02) mutation carriers who took tamoxifen after their first breast cancer." (PMID 19409108, 2009). "Although BRCA2 function is often restricted to DNA recombination and repair, evidence is accumulating that the silencing of this gene might be of particular importance in the pathogenesis of a significant proportion of sporadic breast cancers." (PMID 19442290, 2009). "We observed one BRCA2 variant of unknown significance as defined by the Breast Cancer Information Core (BIC) database and one variant not listed in the BIC database." (PMID 19476645, 2009). "These patients carry mutations in either BRCA1 or BRCA2 genes, but there also are familial breast cancer patients who do not carry mutations in BRCA1/2 and presumably have mutations in another unknown gene or gene(s) (termed non-BRCA1/2 or BRCAX patients)." (PMID 19995430, 2009). "Mammographic density, a strong risk factor for breast cancer, has been positively associated with the ratio of IGF1 to insulin-like growth factor binding protein (IGFBP)-3 in premenopausal women, and has been shown to modify the breast cancer risks in BRCA1 and BRCA2 mutation carriers." (PMID 19843326, 2009). "We compared expression profiles of irradiated LCLs from BRCA1 and BRCA2 carriers to those of non-BRCA1/2 BRCAX familial breast cancer patients, an appropriate reference group for the proposed evaluation of unclassified variants identified in familial breast cancer patients." (PMID 18497862, 2008). "We assessed if gene expression profiles could distinguish between BRCA1 or BRCA2 pathogenic truncating and missense mutation carriers and familial breast cancer cases whose disease was not attributable to BRCA1 or BRCA2 mutations (BRCAX cases)." (PMID 18497862, 2008). "There is much need for markers that could be used to distinguish patients and families who are likely to carry a BRCA1/BRCA2 germline mutation from mutation-negative families and from breast cancer patients in general." (PMID 18275599, 2008). "These considerations apply to sporadic breast cancer but may also provide insights into the mechanisms of high-penetrance susceptibility genes since risk variants at low-penetrance loci also contribute to the risk of BRCA1 and BRCA2 mutation carriers." (PMID 19094230, 2008). "In a case–control study of 965 BRCA1 and 280 BRCA2 pairs, breast feeding did not influence breast cancer risk in BRCA2 carriers, but BRCA1 carriers who breast fed for over 1 year were less likely to have had breast cancer than those who never breast fed (OR=0.55, 95% CI 0.38–0.80)." (PMID 17213823, 2007). "Among families with high recurrence of breast cancer (≥ 3 cases in first-degree relatives), those from North Sardinia shared the same haplotype whereas the families from French Canadian and Jewish-Yemenite populations presented distinct genetic assets at the BRCA2 locus." (PMID 17640379, 2007).
breast cancer (continued). "A clear genotype–phenotype correlation exists for BRCA2 mutations, where the central part of the gene (nt 3035–6629 in exon 11) is named the ovarian cancer cluster region (OCCR) because mutations within it are associated with an increased ovarian: breast cancer ratio." (PMID 17213823, 2007). "Interestingly, of the six prostate cancer patients carrying disease-associated BRCA2 mutations, 50% were diagnosed before age 50 and most had no family history of prostate cancer (five out of six) or breast cancer (four out of six)." (PMID 17700570, 2007). "However, the relationships between induced or spontaneous abortions and breast cancer risk in BRCA1 or BRCA2 carriers have not been well studied." (PMID 16563180, 2006). "Furthermore, in our study we observed a protective effect of induced abortions on breast cancer risk in BRCA2 (but not in BRCA1 carriers) and the direction of the observed effect is opposite to that which we would expect from recall bias." (PMID 16563180, 2006). "Specifically, in a study comparing mammography among 34 BRCA1 or BRCA2 mutation carriers with breast cancer vs. disease-free controls, false-negative mammography correlated independently with BRCA1/2 mutation, the histological feature of prominent pushing margins, and high breast density." (PMID 16800895, 2006). "Because BRCA1 and BRCA2 mutation carriers are susceptible to a much higher risk of breast cancer than non-carriers, the corresponding absolute differences in risk between parous and nulliparous carriers may be substantial." (PMID 17187672, 2006). "A potential criticism of our line of thinking could be that there is no haploinsufficient effect of a BRCA1 or BRCA2 mutation, and that anti-oestrogen treatment functions only as a secondary preventer of breast cancer." (PMID 16538216, 2006). "The prevalence of BRCA1 and BRCA2 mutations (approximately 1:500, but higher in Ashkenazi Jewish individuals) indicates that they are unlikely to account for more than 3% to 5% of all breast cancers." (PMID 16507150, 2006). "Lakhani and colleagues studied the pathology of 82 familial breast cancers not attributable to BRCA1 or BRCA2 mutations, and they found these non-BRCA1/2 cancers to be of lower grade, to show less pleomorphism and to have a lower mitotic count than sporadic cancers or BRCA mutation-positive cancers." (PMID 15642173, 2005). "Germline mutations in the BRCA1 (MIM#113705) and BRCA2 (MIM#600185) genes account for genetic predisposition and increased risk for breast and ovarian cancer in the majority of families with inherited predisposition to both these neoplasms and in 20–40% of families with site-specific breast cancer." (PMID 15756275, 2005). "Similarly, ovarian ablation has been shown to reduce recurrence and mortality in breast cancer patients, and prophylactic oophorectomy has been shown to significantly reduce breast cancer incidence in high-risk women, including BRCA1 and BRCA2 mutation carriers." (PMID 16280052, 2005). "The number of women in the present study with a first-degree family history of breast cancer who tested negative for BRCA1/BRCA2 mutations (71 cases, 27 controls) does not offer adequate power to detect differences in the frequency of CHEK2 variants within this stratification." (PMID 15535844, 2004). "Thus far, the most convincing evidence for an association between the 1100delC variant and breast cancer risk is in families who do not carry BRCA1/BRCA2 germline mutations." (PMID 15535844, 2004). "One individual with nonmedullary thyroid cancer (and breast cancer) carried a BRCA2 mutation." (PMID 14735197, 2004). "Several studies have investigated the prevalence of BRCA1 and BRCA2 mutation in series of breast cancer cases unselected for FH in nonfounder populations (i.e. excluding populations such as the Ashkenazi Jewish or Icelandic populations where there are prevalent founder mutations)." (PMID 15381934, 2004).